TADA1 (transcriptional adaptor 1)
Description:
Probably involved in transcriptional regulation.
Synonyms: STAF42; TADA1L; ADA1; hADA1; HFI1
Tractability: PROTAC: ubiquitination databases record sites on it; its protein half-life has been measured.
Gene: Protein-coding gene on chromosome 1 (166,856,510 to 166,876,360, reverse strand). Ensembl gene ENSG00000152382.
Subcellular location: Nucleus
Subcellular location (Human Protein Atlas): Nucleoplasm; Cytosol; Focal adhesion sites
Pathways (Reactome):
Chromatin organization: HATs acetylate histones
Gene Ontology:
Molecular function: transcription coactivator activity
Biological process: positive regulation of DNA-templated transcription; regulation of DNA repair; regulation of RNA splicing; regulation of transcription by RNA polymerase II
Cellular component: nucleoplasm; nucleus; SAGA complex; SAGA-type complex
Genetic constraint (gnomAD): Loss-of-function variants: 23 observed, 40.26 expected, observed/expected ratio (o/e) 0.57, 90% interval 0.41 to 0.81. The upper end of that interval is the gene's LOEUF score, 0.81, which puts it in group 3 of 6, group 1 being the genes least tolerant of losing a copy. Missense variants: 352 observed, 428.76 expected, observed/expected ratio (o/e) 0.82, 90% interval 0.75 to 0.9. Synonymous variants: 137 observed, 160.44 expected, observed/expected ratio (o/e) 0.85, 90% interval 0.74 to 0.98.
Homologues: Orthologues: chimpanzee TADA1 (100% identical), macaque TADA1 (100% identical), pig TADA1 (99% identical), dog TADA1 (99% identical), mouse Tada1 (96% identical), rat Tada1 (91% identical), guinea pig TADA1 (90% identical), rabbit TADA1 (85% identical), tropical clawed frog tada1 (81% identical), zebrafish TADA1 (39% identical), Drosophila melanogaster Ada1-1 (27% identical), Drosophila melanogaster Ada1-2 (27% identical).
Diseases named in the same sentence as TADA1 in open-access papers:
TADA1 is named in the same sentence as 10 diseases in open-access papers, as found by Europe PMC text mining. Sharing a sentence is not in itself a finding about the gene and the disease. The quoted sentences say what the papers report.
lung squamous cell carcinoma (2 papers, 2023). "Upregulation of TADA1 was reported to promote lung squamous cell carcinoma progression." (PMID 36930369, 2023). "However, inhibiting miR-150-5p and activating Transcriptional Adaptor 1 (TADA1), now LINC00511 can enhance the proliferation and migration of lung squamous cell carcinoma." (PMID 37888204, 2023).
melanoma (2 papers, 2019 to 2023). A malignant, usually aggressive tumor composed of atypical, neoplastic melanocytes. "Interestingly, it predicted positive association in breast cancer through co-relation with MYL6, RABAC1 and other genes, while negatively regulating ATL2, ICE2 and TADA1 in melanoma and HCC." (PMID 30857225, 2019). "The lentivirus-encapsulated GeCKO library was transfected into melanoma cells, and new melanoma resistance-related genes NF2, CUL3, TADA2B, and TADA1 were identified by vemurafenib resistance screening." (PMID 37834313, 2023).
neuroblastoma (1 paper, 2024). Neuroblastoma (NB) is the most common solid, extracranial childhood tumor. "Among the most enriched differential gene dependencies observed in MYCN-amplified neuroblastoma as compared to all other solid tumor lineages were TADA2B, TADA1, SUPT20H, and TAF5L, along with several other members of the core and KAT modules." (PMID 38820154, 2024).
ovarian carcinoma (1 paper, 2025). A malignant neoplasm originating from the surface ovarian epithelium. "In a similar study with the GeCKO library in the A2780 and SKOV3 ovarian cancer cell lines, ZNF587B, TADA1, SEMA4G, POTEC and USP17L20 were identified as candidate genes; among these, loss of ZNF587B and SULF1 gene expressions were associated with cisplatin resistance." (PMID 40242936, 2025).
cancer (1 paper, 2019). A tumor composed of atypical neoplastic, often pleomorphic cells that invade other tissues. "To validate DeepCpf1 in the design of guide RNAs libraries, we took the protein-coding genomic sequence of TADA1, an essential gene for cell viability in cancer and pluripotent stem cells, from the UCSC Genome Browser and used DeepCpf1 to screen for both CRISPR activity and specificity." (PMID 31195957, 2019).
TADA1 also shares sentences with these, for which no sentence is quoted: infection (2 papers); anemia (1); breast carcinoma (1); diabetes (1); gastric cancer (1).